ABCB5 (ATP binding cassette subfamily B member 5)
Diseases named in the same sentence as ABCB5 in open-access papers (continued):
Sharing a sentence is not in itself a finding about the gene and the disease.
melanoma (continued). "We also excluded the stem melanoma-stem marker ABCB5 that, despite the contextual effective CD146 and ABCB5 enrichment, was rare, even in the ABCB5-enriched CMC fraction." (PMID 34830300, 2021). "Preliminary findings documented the efficiency of enrichment and isolation of CMCs from plasma of a series of 21 patients affected by early or advanced stage melanoma, based on CD146 or ABCB5 expression, or a combination thereof." (PMID 34830300, 2021). "Tumorigenic heterogeneity within the melanoma vertical growth phase (VGP) is due to a subpopulation of human melanoma cells expressing the multidrug resistance transporter, ABCB5." (PMID 34830300, 2021). "This switching led to the upregulation of multiple melanoma stem cell markers including nerve growth factor receptor (NGFR) 46, ATP-binding cassette sub-family B member 5 (ABCB5) 47 and aldehyde dehydrogenase (ALDH) activity." (PMID 32483452, 2020). "ABCB5 and CD133 have been proposed to be stem cell markers on the sentinel lymph nodes of melanoma patients." (PMID 33114317, 2020). "Nestin, CD133, receptor activator of NF-k B (RANK), ATP-binding cassette sub-family B member 5 (ABCB5), CD20, and CD271 have been identified as potential candidates for the identification of melanoma-initiating cells." (PMID 31330795, 2019). "For ABCB5, 210 genes were differentially expressed in CTC fractions derived from melanoma patients relative to those from controls, with 187 genes significantly up-regulated and 23 genes significantly down-regulated." (PMID 30769764, 2019). "Our results showed reduction in CD133 and ABCB5 markers in CAP and SN co-treated group which signifies the damage in melanoma stem cells." (PMID 31126298, 2019). "Firstly, the expression of a subset of melanoma genes was investigated by RT-PCR in MCSP-enriched and ABCB5-enriched CTCs isolated from a total of 59 blood draws from 39 melanoma cases." (PMID 30769764, 2019). "It was previously shown that GH action in GHR+ human melanoma cells upregulates while GHR knockdown suppresses the ABC-transporter system, especially ABCB1, ABCB5, ABCB8, ABCC1, ABCC2, ABCG1, and ABCG2 differentially in a drug-dependent manner." (PMID 31547367, 2019). "Decrease in EMT markers (E-cadherin, YKL-40, N-cadherin, SNAI1) were seen with simultaneously decline in melanoma cells (BRAF, NAMPT) and stem cells (CD133, ABCB5) markers." (PMID 31126298, 2019). "In melanoma cells, ATP-binding cassette (ABC) transporters, in particular of type ABCB5, were found to mediate resistance to the chemotherapeutics doxorubicin and temozolomide." (PMID 31035967, 2019). "In this study, we observed that MCSP and ABCB5 CTC fractions had 11 and 10 genes commonly expressed with single melanoma tumour cells, respectively." (PMID 30769764, 2019). "Subsequently, this list of melanoma-expressed genes was compared against the up-regulated genes in the MCSP- and ABCB5-enriched CTC fractions." (PMID 30769764, 2019). "Differential expression of the melanoma specific transcripts was observed between and within CTC fractions enriched with MCSP- or ABCB5-coated beads, suggesting the molecular heterogeneity of these two CTC subpopulations." (PMID 30769764, 2019). "ABCB5 was differentially expressed in early passages of TMZ-treated and BRAF inhibitor-treated melanoma cells." (PMID 29929490, 2018). "Recently identified melanoma stem cell markers include JARID1B (jumonji, AT-rich interactive domain 1B), ABCB5 (ATP-binding cassette subfamily B (MDR/TAP) member 5), ABCG2 (ATP-binding cassette subfamily G member 2), and MDR1 (multi-drug resistance 1)." (PMID 29455657, 2018). "Re-sensitization of melanoma cells to PLX was tested by p-ERK inhibitor PD58059 and ABCB5 knockdown by ABCB5 siRNA, respectively." (PMID 29929490, 2018).
melanoma (continued). "There are several key stem cells markers specified for malignant melanoma: CD20, CD133, ABCB5, CD271 and ALDH1A." (PMID 29455657, 2018). "ABCB5 is expressed in malignant melanoma initiating cells (MMIC), a subset of melanoma cells with a stem cell phenotype." (PMID 29929490, 2018). "Targeting melanoma cells that express CD133, CD271 or ABCB5 has been shown to block processes of migration, metastasis and tumor maintenance." (PMID 30053879, 2018). "In ABCB5+ melanoma cells, STAT is responsible for the transcription of the tumor suppressor promyelocytic leukemia protein, which inhibits proliferation of malignant melanoma initiating cells." (PMID 28798748, 2017). "A recent study provided evidence that ABCB5 promotes metastatic activity by melanoma cells; in fact, ABCB5+ cells have more metastatic activity than ABCB5− cells, this difference being related to a higher migratory capacity of ABCB5+ cells." (PMID 29156643, 2017). "In melanoma, different markers have been employed to characterize the putative melanoma CSC and, particularly, CD133, CD271, CD146, ALDH, ABCB5, ABCG2, Nestin and CD117 were considered." (PMID 28125999, 2017). "Rh123low (Low Rhodamine 123) cells exhibit stem-like phenotype correlate with enhanced levels of HIF1α, Oct4 and ABCB5 and reduced level of Cyclin D1 and CDK4 which define the quiescent and chemoresistance properties of CSCs in melanoma." (PMID 28137308, 2017). "In the case of melanoma, cells expressing the surface markers CD133 and ABCG2, ABCB5 and CD271 have been examined, as well as the intracellular enzyme Aldehyde Dehydrogenase." (PMID 27613604, 2016). "In particular, ATP-binding cassette sub-family B member 5 (ABCB5), the mediator of chemoresistance, is overexpressed by CSCs in diverse human malignancies, including melanoma stem cells." (PMID 26910836, 2016). "CD133 has been shown to be in part co-expressed with ABCB5 and CD271, and has been used as a stem cell and cancer stem cell marker in melanoma, glioblastoma, colorectal cancer and others." (PMID 27613604, 2016). "Consistent with the observed reduction in ABCB5, upon APP downregulation aggressive melanoma cell lines became sensitive to chemotherapeutic drugs to which they were not previously sensitive." (PMID 26840089, 2016). "ABCB1, ABCB5, ABCG2: melanocytes and melanoma cells were found to variably express some of these markers (particularly ABCB5) but they were more frequently expressed in melanospheres and cell lines." (PMID 26978405, 2016). "In malignant melanoma, the drug transporter and chemoresistance mediator ABCB5 was identified as a novel molecular marker for a distinct subset of chemoresistant, stem-cell phenotype-expressing tumor cells, indicating that ABCB5 may be a specific target to enhance cytotoxic efficacy." (PMID 25351876, 2015). "Analysis of mRNA expression levels of CD271, CD133, ABCB5, SOX2 and melanoma markers SOX10, NES and TYR, MART-1 and MITF-M revealed a strong heterogeneity among the PM tissue samples." (PMID 24799129, 2014). "First, we wanted to determine if two of the most studied Melanoma Initiating Cell (MIC) markers, ABCB5 and CD271 were shared by the same population or were expressed by different cell populations." (PMID 25105565, 2014). "Using melanoma cell lines and melanoma cells freshly isolated from patient biopsies, we investigated the relationship between ABCB5+, CD271+ and low-MITF, expressing populations that were reported to display melanoma initiating cell properties." (PMID 25105565, 2014). "Further, prospective studies measuring circulating melanoma cells in 230 patients with melanoma and 152 healthy controls identified two other potential prognostic serological CTC markers; MLANA, a melanocyte marker, and ABCB5, a stem-like cell marker." (PMID 27429260, 2014).
melanoma (continued). "Conversely, in SAN melanoma cells overexpressing FKBP51, a sevenfold increase in ABCB5 mRNA (grey histogram) was measured (left), compared with wild-type (WT) or empty-vector stably transfected cell (EV) mRNA levels." (PMID 23559012, 2013). "The ectopic overexpression of Oct-3/4 in melanoma cell lines was also effective to enhance their expression of stem cell-like markers such as CD271, MDR1, ABCG2, ABCB5, Kruppel-like factor 4 (KLF4) and Nanog and self-renewal capacity." (PMID 23301832, 2013). "Expression of MCAM, MCSP, ABCB5, CD271 and CD45 was demonstrated in A2058 melanoma cells by immunofluorescence." (PMID 22978632, 2012). "Using a melanoma xenograft model (WM266-4), we observed in vivo that ABCB5-expressing cells are enriched after a temozolomide treatment that induces a significant tumor regression." (PMID 22675422, 2012). "Further on, xenotransplantation experiments validated certain CSC markers like ABCB5 for melanoma, CD133 for melanoma, lung and colon cancer and CD20 for melanoma." (PMID 20459772, 2010). "In particular, ABCB5 is overexpressed in melanoma, and ABCG2 is expressed by a subcellular CD133-positive melanoma cells." (PMID 21203549, 2010). "On the other hand, pretreatment of WM35 melanoma cells, expressing ABCB5 but not ABCB1, with verapamil resulted in increased intracellular concentration of doxorubicin, suggesting the inhibition of this transporter by verapamil." (PMID 39267923, 2024). "For instance, ABCB1 expression has been linked with increased metastasis in prostate cancer, uveal melanoma, and breast cancer patient cohorts, while the expressions of ABCB5 and of ABCC1 were up-regulated in metastases of patients and patients with melanoma, respectively." (PMID 37851804, 2023). "Here, we focused on the detection of noncanonical peptides derived from a novel ORF in the ABCB5 melanoma marker, from which we recently identified one peptide in the OD5P DDA immunopeptidome that was confirmed to be immunogenic." (PMID 33845167, 2021). "When applying multiparametric flow cytometry, it was also presented that CMCs detected based on the limited expression of MCAM, MCSP, ABCB5, receptor activator of NF-κB (RANK), and CD271 markers were far more abundant in melanoma, especially in late-stage patients in comparison to healthy controls." (PMID 34575876, 2021). "ABCB5, as melanoma-stem marker of slow-cycling population of tumor cells with self-renewal differentiation and proliferation capabilities, characterizes the S-CMC subpopulation, the only fraction that showed ABCB5, TyrOH, and VEGF expressions." (PMID 32548126, 2020). "We found that ABCB5 was differentially co-expressed in a cluster of 0D5P cells with the transcription factor MITF and CTNNB1, whose expression may be enriched in melanoma stem-cell populations." (PMID 32157095, 2020). "Other potential markers that could be used for the identification of melanoma CSCs are members of ABC family (ABCG2, ABCB5), CD166, and nestin." (PMID 33424978, 2020). "The findings regarding the drug-induced enrichment of strongly ABCB5-positive external SK-MEL-28 and HaCaT cells as well as the lack of effect on internal melanoma cells were confirmed by another anti-ABCB5 antibody." (PMID 31035967, 2019). "Based on ABCB5 immunofluorescence signal intensity profiles, docetaxel led to higher ABCB5 immunofluorescence signals in the external but not the internal melanoma cells." (PMID 31035967, 2019). "We do not think that internal melanoma cells would have been unable to increase ABCB5 expression, because – contrary to our expectation – they typically showed lower ABCB5 signals than external ones before treatment." (PMID 31035967, 2019). "Similarly, the up-regulated genes in the ABCB5 CTC fractions were involved in metastasis (CALU, CYB5R1, DUSP3, CREG1, ENDOD1), tumour growth, and/or melanoma biology (H1F0, SCNA, WIPI1, TXN2)." (PMID 30769764, 2019).
melanoma (continued). "By Western blot analysis we could observe that ABCB5 and CD44 are expressed in both melanoma cell lines; conversely, CD271 is expressed in A375 cells, while no protein band could be detected in BLM cells." (PMID 29330434, 2018). "Our current study also showed that ABCB5 was overexpressed in two of the BRAF inhibitor-resistant melanoma cells (A2058 PLXr and SK-MEL-28 PLXr) but not A375 PLXr cells." (PMID 29929490, 2018). "In addition, ABCB5+ and CD133+ melanoma specific CSCs preferentially express VEGFR1 and VEGF that are essential for VM in human melanoma cells." (PMID 28137308, 2017). "Melanoma specific CSCs carry specific marker (CD133, CD20, ABCB5, CD271 and ALDH1) or antigens, so targeting these cells using monoclonal antibodies could help to combat melanoma growth." (PMID 28137308, 2017). "Furthermore inhibition of ABCB5 can impair tumor growth in vivo and reverse the resistance of B16F10 melanoma cells to chemotherapeutic drugs in vitro." (PMID 26910836, 2016). "As opposed to glycolysis and glutaminolysis, energy metabolite levels were not significantly affected by ABCB5 expression in G3361 melanoma cells, whereas increasing steroid resistance in WEHI7.2 cells generally resulted in improved ATP production." (PMID 27560924, 2016). "We recently found that ABCB5 (ATP-Binding Cassette, Sub-Family B (MDR/TAP), Member 5), a cell-surface marker for melanoma-initiating cells (MICs), is functionally required for MIC-driven melanoma growth." (PMID 27560924, 2016). "First, ABCB5 and CD271 appear to mark different melanoma cell populations, excepted in 501mel." (PMID 25105565, 2014). "Indeed, over expression of MITF in human melanoma cells increase the expression of ABCB5 and ChIP experiment showed that MITF binds to the ABCB5 gene." (PMID 25105565, 2014). "The presence of such an ABCB5+ subpopulation is not restricted to the WM-266-4 cell line model and was detected in most of the tested melanoma cell lines, with a proportion ranging from 1 to 5% of the total cells." (PMID 22675422, 2012). "Comparison of immunoexpression of CD133, ABCB5, CD166 and Nestin in tissues with different primary lesion thicknesses revealed greater expression of CD133 and CD166 in primary melanomas that demonstrated >1.00 mm thickness compared to those that were less than ≤1.00 mm." (PMID 22922842, 2012). "Expression of CD271, ABCB5, CD133, and CD20 by melanoma CSCs has been reported." (PMID 21487158, 2011). "Interestingly, B16-F1 and B16-F10 cells induced expression of CD133, ABCB5, CD44 and CD24, which are expressed in mouse melanoma CSC-like cells during tumorigenesis, and ectopic generation of GDF3 increased the CD24 expression." (PMID 20950440, 2010). "Furthermore, in the immunohistochemistry of melanoma, cells expressing ABCB5 correlated with non-melanized regions." (PMID 39267923, 2024). "In contrast, ABCB5 expression was not detectable in two amelanotic melanoma cell lines." (PMID 39267923, 2024). "Indeed, tumor cells which express markers associated with the stem cell functional phenotype, such as Notch, Wnt, ABCB5, CD133, CD166, nestin, and c-kit, and significantly contribute to the establishment of tumor vasculature have been observed in aggressive melanoma and glioblastoma." (PMID 34299320, 2021). "This suggests that ABCB5 may not be a useful therapeutic target for patients with BRAF inhibitor-resistant melanoma." (PMID 35048028, 2021). "For example, the immunogenic noncHLAIp derived from the dORF in the ABCB5 gene was moderately expressed in only 37% of the melanoma cells compared to the expression of the TYR and TYRP1 genes, both of which were highly and uniformly expressed and produced confirmed immunogenic epitopes." (PMID 32157095, 2020). "Additionally, the significant enrichment of melanoma EMT-involved pathways, such as the MTORC1_SIGNALING and PI3K_AKT_MTOR_SIGNALING hallmarks in these CTC fractions, suggests an invasive transcriptional programming of ABCB5 CTCs." (PMID 30769764, 2019).
melanoma (continued). "Deliberately disrupting or inhibiting ABCB5 in melanomas might not be sufficient to improve the therapeutic resistance to BRAF inhibitors." (PMID 29929490, 2018). "Deliberately disrupting or inhibiting ABCB5 in melanomas may not be sufficient to improve the therapeutic resistance." (PMID 29929490, 2018). "Studies carried out in vitro and in patients’ sample specimens provided evidence that ABCB5-expressing cells selectively survive when melanoma cells are exposed to melanoma chemotherapeutics, including vemurafenib, the BRAF inhibitor used for treatment of BRAF V600E melanomas." (PMID 29156643, 2017). "In contrast, a study of 22 heterogeneously expressed markers from stage II, III and IV patient melanomas, including CD271, ABCB5, and CD133 reported that all cells, whether marker-positive or -negative, had tumourigenic capacity when assayed in highly immune-deficient hosts." (PMID 27613604, 2016). "The observed higher levels of glycolysis metabolites in ABCB5-expressing melanoma cells are in agreement with most earlier studies carried out on other cancer stem cells and stem-like cancer cells, as well as on cancer cells expressing ABC transporters other than ABCB5." (PMID 27560924, 2016). "In addition, apoptosis, label-retention, frequency of ABCB5-positive cells and the expression of Wnt/β-catenin signaling target genes, MITF and c-MYC, were assessed in melanoma populations treated with compounds selected as either highly anti-clonogenic or highly cytotoxic." (PMID 24595456, 2014). "However, no increased tumorigenicity has been observed when CD271+ or ABCB5+ melanoma cells were injected into NSG mice lacking NK Cells." (PMID 25105565, 2014). "However, we (as well as other groups) did not observe consistent but highly variable expression of ABCB5 in the melanoma SP." (PMID 24098529, 2013). "The existence of melanoma-initiating cells has only been recently proposed, with the description of a subpopulation of melanoma cells expressing markers such as CD20, CD133, CD24, CD271, or the ABC transporter (ATP-binding cassette) involved in drug efflux (ABCB5), ALDH1A." (PMID 24416617, 2013). "Interestingly, ABCB1, ABCG2, ABCB5 and ABCC1 have been found important in melanoma chemoresistance." (PMID 24098529, 2013). "In addition, in our model neither ABCB5+ melanoma initiating cells nor CSCs can support the enhanced immune-modulating capacity of spheroid cells, given that our spheroids were not prominently enriched with such cells." (PMID 21526207, 2011). "The presence of spontaneous specific T cells recognizing the noncHLAIp derived from the dORF of the ABCB5 gene in both peripheral blood and TILs suggests no central tolerance and that this target could allow immune targeting of the melanoma stem-cell subpopulation to curtail tumor growth." (PMID 32157095, 2020). "Identification and characterization of CSCs in melanoma is challenging due to tumor heterogeneity and the lack of specific markers (CD271, ABCB5, ALDH, Nanog) and the ability of cells to dynamically change their phenotype." (PMID 40806546, 2025). "Our data indicate that ABCB5 was overexpressed in BRAF resistant SK-MEL-28PLXr and A2058PLXr melanoma cells but not BRAF-resistant A375PLXr cells." (PMID 29929490, 2018). "In fact, it was shown that ABCB5+, but not ABCB5− melanoma cells express VEGF-R1; in vitro studies have shown that VEGF induced CD144 expression in ABCB5+ cells." (PMID 29156643, 2017). "The expression of ABCB5 was not detectable by immunostaining, western blot, or flow cytometry analysis in either spheroid or adherent cells from SLM8 and Mela1 melanoma." (PMID 21526207, 2011). "Another study tested the impact of blocking the ABCB5 transporter on recurrent melanoma, but found that knockdown of ABCB5 did not re-sensitize BRAF inhibitor-resistant melanoma cell lines, in spite of the fact that ABCB5 is highly expressed in malignant melanoma-initiating cells." (PMID 35048028, 2021).